SDHAP1 (SDHA pseudogene 1 )
Synonyms: SDHAL1; SDHALP1
Gene: Long non-coding RNA gene on chromosome 3 (195,959,281 to 195,990,325, reverse strand). Ensembl gene ENSG00000290763.
Diseases named in the same sentence as SDHAP1 in open-access papers:
SDHAP1 is named in the same sentence as 7 diseases in open-access papers, as found by Europe PMC text mining. Sharing a sentence is not in itself a finding about the gene and the disease. The quoted sentences say what the papers report.
ovarian carcinoma (8 papers, 2020 to 2026). A malignant neoplasm originating from the surface ovarian epithelium. "The functional analysis indicated that the SDHAP1/miR-4465/EIF4G2 regulatory axis was linked to the apoptosis induced by paclitaxel in ovarian cancer." (PMID 41362671, 2026). "Succinate dehydrogenase complex flavoprotein subunit A pseudogenene 1(SDHAP1) is located on chromosome 3, encoding lncRNA SDHAP1 which is associated with chemoresistance in ovarian cancer." (PMID 34796116, 2021). "Prior research has indicated a connection between the lncRNA SDHAP1 and resistance to chemotherapy drugs in ovarian cancer, even though research specifically examining this relationship remains scarce." (PMID 41362671, 2026). "Investigations have shown that SDHAP1 is overexpressed in ovarian cancer cell lines that are resistant to paclitaxel, such as Hey-8 and SKOV3, and this increased SDHAP1 expression is associated with decreased levels of miR-4465." (PMID 41362671, 2026). "Recently, there have been reports of the abnormal increased expression of the lncRNA succinate dehydrogenase complex flavoprotein subunit A pseudogene 1 (SDHAP1) in ovarian cancer cell lines that are resistant to the chemotherapy drug paclitaxel." (PMID 41362671, 2026). "Silencing of SDHAP1 induced re-acquirement of chemo-sensitivity to PTX in ovarian cancer cells in vitro." (PMID 34796116, 2021). "Recently, it was found that lncRNA SDHAP1 upregulated the expression of EIF4G2 by reducing miR-4465 levels in ovarian cancer cells." (PMID 33153035, 2020). "Moreover, inhibiting the expression of SDHAP1 was found to restore sensitivity to paclitaxel chemotherapy in ovarian cancer cells in laboratory studies." (PMID 41362671, 2026). "Nevertheless, research on the regulatory role of SDHAP1 in chemotherapeutic resistance in ovarian cancer is scarce, and the precise mechanisms are still unknown." (PMID 41362671, 2026). "A recent study showed that lncRNA SDHAP1 upregulated the expression of EIF4G2 by reducing miR-4465 levels in ovarian cancer cells, which suggests that the pseudogenes may regulate gene expression through microRNAs." (PMID 37165454, 2023). "Depletion of lncRNA SDHAP1 stimulated paclitaxel sensitivity in ovarian cancer cells." (PMID 36105363, 2022). "Unexpectedly, SDHAP1 is classified as a lncRNA in ovarian cancer." (PMID 33153035, 2020). "The anticancer effect of SDHAP1 was accordant with that SDHAP1 upregulated EIF4G2 level by sponging miR-4465 and therefore promoted the PTX-induced apoptosis in ovarian cancer." (PMID 36438489, 2022). "Mechanically, lncRNA SDHAP1 sponged miR-4465 and promoted the expression of EIF4G2, which conferred paclitaxel-induced cell apoptotic death in ovarian cancer cells." (PMID 36105363, 2022). "In mechanism, SDHAP1 upregulates EIF4G2 expression through sponge miR-4465, thereby promoting PTX induced apoptosis in ovarian cancer cells." (PMID 34796116, 2021). "Studies have been shown that SDHAP1 was upregulated in PTX-resistant SKOV3 and Hey-8 ovarian cancer cell lines, while miR-4465 levels were down-regulated." (PMID 34796116, 2021). "The regulatory network involving the interactions between SDHAP1, miR-4465, and EIF4G2 could represent a promising therapeutic target for treating ovarian cancer that has developed resistance to paclitaxel chemotherapy." (PMID 41362671, 2026). "Mechanistically, SDHAP1 was shown to increase the expression of the protein eukaryotic translation initiation factor 4 gamma 2 (EIF4G2) by acting as a decoy for miR-4465, which in turn promoted paclitaxel-induced cell death in ovarian cancer cells." (PMID 41362671, 2026). "The regulatory networks involving SDHAP1, miR-4465 and EIF4G2 participate may be potential therapeutic targets for PTX-resistant ovarian cancer." (PMID 34796116, 2021).
tumor (3 papers, 2020 to 2025). "In OC, HMGA1P6, CTSLP8, and SDHAP1 are known to competitively bind to their paralogs, influencing tumour metastasis and paclitaxel resistance." (PMID 40000433, 2025). "The composite plot indicated that SDHAP1, SDHAP3, DDX12P, CLUHP3, and RRN3P3 demonstrated high expressions in the low-risk subtype, which were categorized as tumor-suppressor pseudogenes in our study." (PMID 36438489, 2022). "Compared to HPV negative, patients with HPV positive had significantly higher expressions of oncogene pseudogenes (SDHAP1, SDHAP3, DDX12P, CLUHP3, and RRN3P3), but there was no prominent difference in the expressions of tumor-suppressor pseudogenes (PDIA3P1, LDHAP4, LDHAP7, EEF1A1P6, and EEF1A1P11)." (PMID 36438489, 2022).
cancer (1 paper, 2023). A tumor composed of atypical neoplastic, often pleomorphic cells that invade other tissues. "SDHAP1, ZDHHC8P1, and DIO3OS were significantly differentially expressed in several cancer types." (PMID 36221911, 2023).
SDHAP1 also shares sentences with these, for which no sentence is quoted: breast carcinoma (1 paper); colon cancer (1); pancreatic cancer (1); squamous cell lung carcinoma (1).